CTLA4 (cytotoxic T-lymphocyte associated protein 4)
Diseases named in the same sentence as CTLA4 in open-access papers (continued):
Sharing a sentence is not in itself a finding about the gene and the disease.
lung cancer (continued). "In this meta-analysis, a total of 9 eligible and original case-control studies, examined the associations of CTLA-4 +49 A/G polymorphism and lung cancer risk." (PMID 33819967, 2021). "All articles addressed lung cancer and polymorphisms of CTLA-4 were searched from the PubMed, EMBASE databases published up to June 29, 2019." (PMID 33819967, 2021). "The immune checkpoint inhibitors (ICIs), by targeting cytotoxic-T-lymphocyte-associated protein 4, programmed cell death 1 (PD-1), or PD-ligand 1, have dramatically changed the natural history of several cancers, including non–small cell lung cancer (NSCLC)." (PMID 35186013, 2021). "There are a very limited number of studies on the association between the CTLA-4 polymorphisms and lung cancer risk." (PMID 33519815, 2020). "The most extensively studied for targeted immunotherapy in lung cancer include inhibitory receptors cytotoxic T-lymphocyte-associate protein 4 (CTLA4), programmed death protein 1 (PD1), and programmed death ligand 1 (PD-L1)." (PMID 32316322, 2020). "The immunomodulatory monoclonal antibodies against cytotoxic T-lymphocyte-associated antigen 4 (CTLA-4) also present the promising results for the treatment of advanced -stages lung cancer patients." (PMID 30103737, 2018). "In a study of 81 lung carcinomas, 46.9% of the tumors overexpressed CTLA4; this showed a trend (p=0.078) in associating with better survival." (PMID 28038471, 2017). "Immunotherapy has brought up new options for lung cancer patients, including blockade of immune checkpoints like cytotoxic T-lymphocyte-associated protein 4 (CTLA-4) and programmed cell death 1 (PD-1)." (PMID 27144518, 2016). "The presented study carried out in NSCLC tissue and blood samples, combining the CTLA-4 expression analysis on mRNA level with gene polymorphic variants, seems valuable as it expands a small amount of data available in lung cancer patients." (PMID 23936819, 2013). "Although the most recently published meta-analysis proved the association between CTLA-4 SNPs and the risk of multiple cancer it included only two reports on lung cancer." (PMID 23936819, 2013). "Ipilimumab, a monoclonal antibody targeting cytotoxic T lymphocyte-associated antigen-4 (CTLA-4), has been explored in combination with other immune checkpoint inhibitors like nivolumab for the treatment of lung cancer, but its use as monotherapy is less common." (PMID 39199653, 2024). "Immune checkpoint inhibitors (ICIs) targeting programmed cell death 1 (PD-1), its ligand (PD-L1), and cytotoxic T-lymphocyte-associated protein 4 (CTLA-4) have emerged as a promising treatment option for lung cancer patients and can dramatically improve clinical outcomes." (PMID 38667328, 2024). "Moreover, polymorphisms observed at several T cell immune checkpoints, such as B- and T-lymphocyte attenuator (BTLA), CTLA-4, and PD-1, which are known for their immunosuppressive roles, have been implicated in modulating susceptibility to lung cancer." (PMID 38983267, 2024). "The immune checkpoint blockade (ICB) therapy including anti-programmed death 1 (PD-1) therapy, anti-programmed death 1 ligand (PD-L1), and anti-cytotoxic-T-lymphocyte-associated protein 4 (CTLA-4) therapy has been proven to be beneficial in some lung cancer patients in clinical trials." (PMID 37465684, 2023). "As neuro-ophthalmic disorders are mostly linked to lung cancer; this could explain why it is less common with anti-CTLA-4 monotherapy." (PMID 36811715, 2023). "In addition, Sandra Demaria from the Weill Cornell Medical College in New York, USA, addressed the enhancement of response to immunotherapy by RT based on combining RT with cytotoxic T lymphocyte-associated protein 4 (CTLA-4) blockade in lung cancer." (PMID 37872395, 2023). "In addition to PD-1 and PD-L1, cytotoxic T-lymphocyte-associated antigen 4 (CTLA-4) also presents promising results in the treatment of advanced-stage lung cancer patients." (PMID 37741993, 2023).
lung cancer (continued). "The identification of immune checkpoint molecules, such as programmed death-1 (PD-1) and programmed death-ligand 1 (PD-L1) and cytotoxic T lymphocyte-associated antigen-4 (CTLA-4), has made immunotherapy one of the most promising curative modalities for lung cancer in recent years." (PMID 36860311, 2023). "The prototypical ICIs for lung cancer, also known as programmed death protein 1 (PD-1), and its ligand, programmed cell death ligand 1 (PD-L1) and cytotoxic T-lymphocyte-associated antigen 4 (CTLA-4), are the most studied ICI targets." (PMID 36672492, 2023). "Lung cancer remains the main cause of cancer death globally, and recently, immunotherapy has been a novel approach for cancer treatment through targets, such as PD-1, PD-L1, and CTLA-4, to enhance the patients’ immune system." (PMID 35522679, 2022). "Immune evasion through upregulation of immune checkpoints such as indoleamine 2,3-dioxygenase (IDO1), cytotoxic T-lymphocyte-associated protein 4 (CTLA-4) and programmed death-ligand 1 (PD-L1) has been identified as an evolutionary trajectory during pre-invasive stages of lung cancer." (PMID 34557196, 2021). "Immune checkpoint inhibitors (ICIs), by targeting cytotoxic-T-lymphocyte-associated protein 4 (CTLA-4), programmed cell death 1 (PD-1), or PD-ligand 1 (PD-L1), have yielded durable anti-tumor responses and long-term remissions in non–small cell lung cancer (NSCLC) and other cancer types." (PMID 35186013, 2021). "Considering the importance of CTLA-4 in tumorigenesis and the limitations of single study, we conducted a comprehensive meta-analysis of published studies to derive a more precise and objective estimation of the relationship between CTLA-4 +49A/G polymorphism and the risk lung cancer." (PMID 33819967, 2021). "Hence, it is plausible that lncRNAs associated with CTLA-4 could potentially contribute to the invasion of lung cancer cells." (PMID 39143529, 2024). "However, the relationship between CTLA-4+49 A/G polymorphism and lung cancer is still unclear." (PMID 33819967, 2021). "ICIs such as CTL-associated protein 4 (CTLA-4), programmed cell death-1 (PD-1)/programmed death-ligand 1 (PD-L1), and their inhibitors, have been known as key factors for overcoming the immunosuppressive conditions in patients with malignancies including lung cancer." (PMID 35008367, 2021). "Increased ICOS expression on CD4+ T‐cells of patients treated with anti‐CTLA‐4 therapies has been seen in non‐small cell lung cancer, bladder cancer, and breast cancer." (PMID 41474629, 2026). "According to the study, it can be found that the combination of radiotherapy and CTLA-4 blocker can significantly improve the disease control rate of lung cancer patients." (PMID 40861450, 2025). "Immunotherapy drugs called immune checkpoint inhibitors, particularly those targeting PD-1/PD-L1 and CTLA-4, have led a ground-breaking revolution in lung cancer treatment." (PMID 40861450, 2025). "We then evaluated its performance on an independent dataset of 150 patients with non–small-cell lung cancer (74 patients treated with anti-PD-L1 and 76 treated with anti-PD-L1 + anti-CTLA-4 from the MYSTIC trial [NCT02453282]; Supplementary Note 2)." (PMID 40025003, 2025). "Although ICIs targeting PD-1 or CTLA-4 have achieved remarkable success in lung cancer treatment recently, their overall efficacy remains limited." (PMID 40855046, 2025). "To date, the US Food and Drug Administration (FDA) has approved various PD-1/PD-L1 inhibitors and CTLA-4 inhibitors for cancer treatment, including in lung cancer patients." (PMID 40469290, 2025). "When MAP is combined with anti‐CTLA4 therapy, it synergistically inhibits the proliferation of colorectal and lung cancer cells, thereby further promoting antitumor effects." (PMID 39499771, 2025).
lung cancer (continued). "As an example of lowering the threshold, additional analyses of existing immune‐mediated drug targets validated the effects of CTLA4 expression on lung cancer and of METTL3 expression on prostate cancer." (PMID 41216857, 2025). "The CTLA-4 inhibitors and PD-1/CTLA-4 bispecific antibodies currently in the clinical trial stage for solid tumors or lung cancer." (PMID 41415276, 2025). "Immune checkpoint inhibitors, which target PD-1/PD-L1 or CTLA-4 pathways to harness the host immune system against malignancies, have revolutionized lung cancer treatment." (PMID 41293168, 2025). "The mechanism by which immune checkpoint inhibitors act on lung cancer mainly involves the regulation of two immune checkpoints, PD-1/PD-L1 and CTLA-4." (PMID 40861450, 2025). "Immunotherapy cohort analysis demonstrated that tumors with high ISG15 expression responded favorably to PD-L1 inhibitors but exhibited resistance to CTLA-4 blockade, findings further validated in lung cancer patients receiving anti-PD-1 therapy." (PMID 40208307, 2025). "A deeper understanding of TME heterogeneity, T-cell exhaustion, and irAE mechanisms will be essential to refine the therapeutic positioning of CTLA-4 blockade within the evolving landscape of lung cancer immunotherapy." (PMID 41303538, 2025). "Since we observed an increase in ILC2 frequency and PD-1 and CTLA-4 expression in mPEs from lung cancer patients, we sought to characterize the soluble and cellular immune composition of the TME." (PMID 40993215, 2025). "Beyond CD8+ T cells, in colon cancer and lung carcinoma models, NR4A1 inhibition has been shown to decrease the suppressive function of Tregs through the reduced expression of CD25 and cytotoxic T-lymphocyte-associated antigen 4 (CTLA4)." (PMID 40508074, 2025). "The enhancement of PD-1/PD-L1 and CTLA-4 expression via the EGFR pathway suggests a potent avenue for immune suppression in lung cancer, exacerbated by ERK and NF-κB pathways." (PMID 39726592, 2024). "According to a recent study, CTLA-4 and PD-1 blockers combination is effective and increases response and survival in several types of cancer including lung cancer." (PMID 38234663, 2024). "This review elucidates the application of dual blockade immunotherapy targeting PD-1/PD-L1 and CTLA-4 in lung cancer, providing a comprehensive overview of the utilization and research advancements in dual ICI combination therapy in this context." (PMID 39068460, 2024). "Prostate cancer, lung cancer, and ccRCC have all been studied using monoclonal antibodies that target different immune checkpoint inhibitors (such as CTLA4, PDCD1, and LAG3)." (PMID 39014265, 2024). "PD-1/PD-L1 and CTLA-4, among the most mature targets within ICIs, are the focus of intense research for their application in lung cancer immunotherapy through bsAbs targeting these checkpoints." (PMID 39068460, 2024). "Emerging evidence from clinical trials investigating CTLA-4 inhibition in lung cancer and other malignancies suggests that discontinuing therapy due to a TRAE or requiring immunosuppression to manage immune-mediated toxicities does not impact OS negatively." (PMID 38871975, 2024). "Immunotherapy employing ICIs that target the PD-L1/PD-1 axis and CTLA-4 has shown significant improvements in the survival of lung cancer patients." (PMID 38655260, 2024). "Immunotherapies using anti-PD-1, anti-PD-L1, and anti-CTLA-4 monoclonal antibodies have revolutionized lung cancer treatment; however, only a few advanced-stage patients respond." (PMID 38983267, 2024). "The expression of PDL1, PD1, and CTLA4 in kidney and lung cancers increased with increased expression of PUSs." (PMID 39162904, 2024). "Previous clinical trials have explored combination therapy strategy of anti-PD-1/PD-L1 and anti-CTLA-4 agents in lung cancer, yet its efficacy remains to be unclear with the inevitable incidence of immune-related adverse events." (PMID 39068460, 2024).
lung cancer (continued). "The authors suggest that this increase is associated with the worst prognosis due to CTLA-4 and/or PD1-L signalization on lung cancers." (PMID 39599846, 2024). "We raised the scarcity of knowledge about CIK cells in combination with anti-PD-L1 and anti-CTLA-4 in lung cancer." (PMID 36982701, 2023). "First-line chemotherapy for lung cancer has advanced with use of PD-1 inhibitors combined with cytotoxic chemotherapy and/or anti-cytotoxic T-lymphocyte antigen 4 (CTLA-4) antibody." (PMID 37658334, 2023). "Lung cancer patients receiving approved anti-CTLA-4 and anti-PD-1 antibodies achieved considerable results, though not to the extent of melanoma patients." (PMID 36982701, 2023). "Recently, several immune check inhibitors (ICIs), such as anti-PD-1/PD-L1/CTLA-4, have been widely applied in lung cancer, which can effectively improve progression-free survival in patients with lung cancer." (PMID 36910658, 2023). "A study of lung cancer with 14 ICB-resistant tumor samples also revealed the homozygous loss of B2M in a patient who acquired resistance to combined anti-PD-L1 and anti-CTLA-4 therapy." (PMID 37614504, 2023). "Accordingly, EC.SENESCENCE.SIG predicts response to anti-PD-L1/PD-1 or anti-CTLA-4 immunotherapy in multiple cancer entities including lung cancer, gastric cancer, urothelial carcinoma, renal cell carcinoma, and basal-cell carcinoma." (PMID 36978029, 2023). "The article by Silvia C Formenti published in 2018, Radiotherapy induces responses of lung cancer to CTLA-4 blockade, has the most global citations." (PMID 37025583, 2023). "Immune checkpoint inhibitors (PD‐1/PD‐L1 and CTLA‐4 blockade) have revolutionized the treatment landscape in non‐small cell lung cancer (NSCLC)." (PMID 37963454, 2023). "Blockade of T cell immune checkpoints via targeting PD1/PD-L1 and/or CTLA-4 puts forward the development of tumor immunotherapy strategies including lung cancer, but the response rates are still limited." (PMID 36823443, 2023). "In humans, lung cancer cell lines exposed to CTLA-4 antibody showed anti-cancer effects, thus becoming a prospect for further research." (PMID 36672492, 2023). "Herein, we describe the relative success of CIK cell therapy (alone and combined with dendritic cells as DC/CIKs) in lung cancer clinical trials and discuss its combination with known immune checkpoint inhibitors (anti-CTLA-4 and anti-PD-1/PD-L1)." (PMID 36982701, 2023). "Immunotherapies, especially PD‐1/PD‐L1 and CTLA‐4 blockade, have revolutionized the treatment paradigm for non‐small cell lung cancer (NSCLC) and become the standard treatment for the early and advanced stages of NSCLC without driving oncogenic mutation." (PMID 37963454, 2023). "Immune checkpoint inhibitors (ICI) (i.e., inhibitors of PD-1/PD-L1 and CTLA-4) are a class of immunotherapy that have been highly successful in treating lung cancer and have become an important part of the lung cancer treatment algorithm." (PMID 37345192, 2023). "In advanced lung cancer, PD-1 blockade therapy and anti-CTLA-4 antibody drug therapy have resulted in long-term survival in 20%–30% of patients, and it is believed that the main mechanism by which T-cell immunity is weakened is T-cell exhaustion." (PMID 37476074, 2023). "In lung cancer patients, miR-4443 has been shown to potentially affect the expression of CTLA-4 and TIGIT, and the overall survival of patients by regulating the ZC3H12D-hsa-miR-4443-ENST00000630242 axis." (PMID 36765782, 2023). "ICI therapy targeting checkpoint molecules, such as PD-1 and CTLA-4, has achieved unprecedented long-term survival benefits in advanced lung cancer." (PMID 37476074, 2023).
lung cancer (continued). "Anti-CTLA-4 (ipilimumab) is also be used in lung cancer because of CTLA-4 as a checkpoint on lymphocytes." (PMID 36874015, 2023). "CTLA-4 blockade has been tested in preclinical cancer mouse models of brain, ovarian, bladder, colon and lung cancer, lymphoma, fibrosarcoma and other cancer types." (PMID 35651800, 2022). "ICIs targeting programmed cell death ligand-1 (PD-1), PD-L1, and cytotoxic T lymphocyte-associated antigen 4 (CTLA-4) are currently the most advanced immunotherapies and have transformed the treatment paradigm for a variety of tumors, including lung cancer." (PMID 35958559, 2022). "The most common primary malignancy in this cohort was lung cancer (33.3%; 22/66); 84.8% (56/66) of patients received anti-PD-1/PD-L1 treatment only, 3% (2/66) received anti-CTLA-4 treatment only, and 12.1% (8/66) received both." (PMID 35681667, 2022). "A further immunotherapy strategy that showed advantage in treating lung cancer is combining PD-1/PD-L1 and CTLA-4 inhibitors." (PMID 36551630, 2022). "In recent years, immunotherapy mainly based on immune checkpoint inhibitors (ICIs), such as anti-PD1/PD-L1 and anti-CTLA-4 antibodies, has significantly altered the landscape of cancer treatment, including lung cancer." (PMID 36046337, 2022). "PD-1/PD-L1 and CTLA-4 inhibitors are the most commonly used ICIs in lung cancer, yet development of resistance to these agents remains an insurmountable challenge." (PMID 35222404, 2022). "Radiotherapy coordinated with CTLA4 blockade to induce T cell's anti-cancer activity in chemotherapy-resistant lung cancer." (PMID 36248827, 2022). "At present, both PD-1/PD-L1 and CTLA-4 blockades have been approved for the treatment of lung cancer; however, the limited efficacy and immune-related adverse events of ICIs, led to the discovery of novel checkpoints molecules." (PMID 36551630, 2022). "Anti–PD-1 along with anti–CTLA-4 inhibitors offer superior toxicity profiles against lung cancer cells, longer overall survival rates, and higher objective response rates when compared with chemotherapy." (PMID 36237320, 2022). "In lung carcinoma mice models, it has been reported that low expression levels of MPHOSPH8 are linked to sensitization to anti-PD-1/CTLA-4 therapies, implying a feasible association of this epigenetic regulator and the suppression of the immune evasion." (PMID 35562916, 2022). "Improving combination therapies and defining optimal strategies for advanced lung cancer will be an opportunity to overcome ICIs resistance and wider use of anti-PD-1, anti- PD-L1 and anti-CTLA-4 antibodies." (PMID 34445735, 2021). "The MYSTIC trial is a phase III trial of patients with lung cancer that uses the same strategy but different drugs, such as Durvalumab (anti-PD-L1) and Tremelimumab (anti-CTLA-4) as first-line therapy." (PMID 34391428, 2021). "Dermatologic toxicities are among the most common immune-related adverse events encountered in daily practice when treating lung cancer with an estimated incidence of 44% following CTLA-4 inhibition and 34% with PD-1/PD-L1 targeting treatment." (PMID 34660286, 2021). "Nonetheless, these BTLA+ lymphocytes, which are also PD-1+, TIM3+, CTLA-4+, and LAG-3+, seem to be terminally exhausted and poorly functional, and are associated to disease progression in lung cancer." (PMID 34532285, 2021). "We next selected an aggressive orthotopic TC-1 lung cancer tumor model, which is primarily resistant to anti–PD-1 or anti–CTLA-4 Abs, as stand-alone therapies." (PMID 33320838, 2021). "These microenvironmental changes set the stage for successful combination treatment with anti-PD1/anti-CTLA4 checkpoint inhibitors in mouse models of pancreatic neuroendocrine and lung cancers." (PMID 33671981, 2021). "Our findings provide a rationale and feasible combined therapeutic approach targeting IL-6 and CTLA-4 in lung cancer patients." (PMID 34093869, 2021).